G6PD (glucose-6-phosphate dehydrogenase)
Diseases named in the same sentence as G6PD in open-access papers (continued):
Sharing a sentence is not in itself a finding about the gene and the disease.
viral infections (29 papers, 2013 to 2025). "In G6PD-deficient patients, acute hemolysis occurs when an elevation of oxidative stress is triggered by viral infection, certain medications, or even fava beans." (PMID 36905446, 2023). "The effects of the G6PD mutation in viral infections have previously been studied in Asia where the Mahidol variant is predominant and has no significant protective role against Dengue." (PMID 37340364, 2023). "Overall, these data indicate that G6PD levels play an important role in regulating the susceptibility to viral infection and the extent of viral replication." (PMID 35071051, 2021). "Cells deficient in G6PD display elevated levels of ROS and an increased susceptibility to viral infection, although the consequences of G6PD modulation during viral infection remain to be elucidated." (PMID 35071051, 2021). "It is known that in vitro cells with G6PD knockdown are more susceptible to viral infections, and during the recent COVID-19 pandemic, G6PD deficiency was seen as an aggravating factor in the clinical picture and prognosis." (PMID 34884340, 2021). "G6PD-deficient cells experience a high level of oxidative stress and an increased susceptibility to viral infections." (PMID 27097228, 2016). "Our findings suggest that the increased susceptibility of the G6PD-knockdown cells to viral infection was due to impaired NF-κB signaling and antiviral response mediated by HSCARG." (PMID 26694452, 2015). "The generated A549-Gi and A549-Sc were used to delineate the mechanism underlying the increased susceptibility of G6PD-deficient cells to viral infection." (PMID 26694452, 2015). "Monocytes from 16 G6PD-deficient subjects showed mean virus infection percentage of 40.868±7.330% at 48 hours post infection." (PMID 24625456, 2014). "This is consistent with evidence that G6PD-deficient individuals may experience hemolysis triggered by viral infections and febrile episodes." (PMID 40966243, 2025). "Despite the existence of well-founded data around the relationship between reactive oxygen species (ROS) and glucose-6-phosphate dehydrogenase (G6PD), current research around G6PD-deficient patients with viral infections, and limitations as a result of their condition, are inadequate." (PMID 36905446, 2023). "The role of G6PD enzyme deficiency in viral infections has been extensively studied." (PMID 37376524, 2023). "Though more research is demanded on the topic, preliminary studies suggest that antioxidative therapy which reduces ROS levels in these patients could prove beneficial in the treatment of viral infections in G6PD-deficient individuals." (PMID 36905446, 2023). "Though more research is demanded on the topic, preliminary studies suggest that antioxidative therapy that reduces ROS levels in these patients could prove beneficial in the treatment of viral infections in G6PD-deficient individuals." (PMID 36905446, 2023). "G6PD deficiency affects cellular functions in nucleated cells, including dysregulated cellular signaling, increased cell senescence or apoptosis and enhanced susceptibility to viral infection." (PMID 27097228, 2016). "We have previously shown that G6PD-knockdown cells are more susceptible to viral infection." (PMID 26694452, 2015). "Glucose-6-phosphate dehydrogenase (G6PD)-deficient cells are highly susceptible to viral infection." (PMID 26694452, 2015). "It is probable that the increased susceptibility to viral infections may be partly due to the impaired immune response of G6PD-knockdown cells." (PMID 26694452, 2015). "Also, deficiency in G6PD gene seems to enhance susceptibility to viral infection." (PMID 34125832, 2021).
viral infections (continued). "Uniquely, it is the first to simultaneously evaluate G6PD enzyme activity and genotype in this population, providing a more complete understanding of genotype-phenotype relationships in the context of acute viral infection." (PMID 40966243, 2025). "Recent studies have demonstrated that G6PD plays a pivotal role in various viral infections, wherein viruses upregulate G6PD to reprogram host metabolism for energy and precursor synthesis." (PMID 41204699, 2025). "Although we see some caspase cleavage when we knock out NF2 and G6PD with sgRNAs, this is likely due to the viral infection since it is also present in the control cells treated with control sgRNA (lane 1)." (PMID 38879607, 2024). "G6PD is increased in different viral infections including the infectious pancreatic necrosis virus, the influenza virus, HIV, and cucumber mosaic virus, white spot syndrome virus, and infectious bursal disease virus." (PMID 35805067, 2022). "In G6PD-deficient patients exposed to SARS-CoV-2, the amount of NADPH is reduced, increasing the susceptibility for viral infection." (PMID 35805067, 2022). "In summary, these findings indicate that G6PD knockdown impairs TNF-α/MAPK/NF-κB/COX-2 signaling as a result of insufficient NOX activation, leading to the eventual increase in susceptibility to viral infection." (PMID 27097228, 2016). "The increase in G6PD during viral infection is essential for maintaining NADPH levels, which are subsequently used and depleted by enzymatic and non-enzymatic antioxidant systems to restore the redox homeostatic imbalance caused by viral infection." (PMID 41415822, 2025). "This suggests that the increase of the G6PD in viral infections is necessary to elevate the NADPH, which is then used and depleted by the enzymatic and non-enzymatic antioxidant system in an attempt to balance the redox homeostasis altered by the viral infection." (PMID 35805067, 2022). "Overall, these results highlight the regulation of G6PD protein during the infection by NRF2 and underscore the interrelationship between glucose metabolism and susceptibility to viral infections during glucose metabolic alterations, supporting the central role of G6PD pathway modulation." (PMID 35071051, 2021). "In the present study, TNF-α was used as a stimulus to elucidate whether G6PD knockdown affects the inflammatory response against viral infection." (PMID 27097228, 2016). "G6PD knockdown can affect viral infection by decreasing the epithelial inflammatory response." (PMID 27097228, 2016). "This study addresses how the G6PD status affects the innate immune response to viral infection." (PMID 26694452, 2015). "Studies suggest that it is the degree of enzymatic deficiency, rather than the mere presence of a G6PD mutation, that critically influences susceptibility to adverse outcomes, especially under conditions of heightened oxidative stress such as severe viral infections." (PMID 41433239, 2025). "G6PD is elevated in different viral infections, e.g., HBV can drive the upregulation of G6PD expression through its X protein-mediated activation of nuclear factor erythroid 2-related factor 2 (Nrf2)." (PMID 41415822, 2025). "Most importantly, we have provided evidence that G6PD plays an important role in activating NOX/MAPK/NF-κB/COX-2 cascade and protects cells against viral infection." (PMID 27097228, 2016). "Exogenous G6PD or IDH1 expression inhibited the expression of HSCARG, resulting in increased expression of TNF-α and MX1 and reduced viral gene expression upon virus infection." (PMID 26694452, 2015). "While G6PD and ADH3 gene were most stable under viral infection (TSV & PBNV), ACT11 was the least stable." (PMID 24167633, 2013). "He did not exhibit other triggers of G6PD hemolysis such as bacterial or viral infections, ingestion of fava beans, or drugs known to induce hemolysis like antibiotics or antimalarials." (PMID 39170996, 2024).
viral infections (continued). "The G6PD status, a determinant of the NADPH/NADP+ ratio, affects cellular HSCARG expression, and modulates the level of NF-κB activation and the expression of antiviral genes in response to viral infection." (PMID 26694452, 2015). "As expected, the PA-X-deficient virus did not cause significant downregulation of ACTB and G6PD transcripts compared to mock-infected cells, and the decrease in POLR2A and MALAT1 transcript was weaker although not significantly different from the WT virus infection." (PMID 38629840, 2024).
cervical carcinoma (26 papers, 2016 to 2025). A carcinoma arising from either the exocervical squamous epithelium or the endocervical glandular epithelium. "For instance, miR-206 was found to be downregulated in high-risk HPV-positive cervical cancer, as its function involved the reduction of cancer growth via the suppression of glucose-6-phosphate dehydrogenase (G6PD) expression." (PMID 31766385, 2019). "Here, we demonstrate that microRNA-1 (miR-1) in association with AGO proteins targets G6PD in HR-HPV-infected human cervical cancer cells." (PMID 27861141, 2016). "Ectopic glucose-6-phosphate dehydrogenase (G6PD) expression may contribute to tumorigenesis in cervical cancer associated with high-risk human papillomavirus (HR-HPV 16 and 18) infections." (PMID 27861141, 2016). "However, the sources and regulators of ectopic G6PD expression in carcinogenic events of HR-HPV-16/18-associated cervical cancer, remain unknown." (PMID 27861141, 2016). "However, whether miRNAs contribute to pathological progression in HR-HPV-associated cervical cancer by targeting G6PD remains unknown." (PMID 27861141, 2016). "DCBLD1 inhibited glucose-6-phosphate dehydrogenase (G6PD) autophagic degradation, activating the pentose phosphate pathway to promote cervical cancer progression." (PMID 40563450, 2025). "Conversely, in HPV16 E6-driven cervical cancer, reduction in lactate production suppressed G6PD K45 lactylation, increasing G6PD enzymatic activity and similarly activating the PPP, which contributes to cancer progression." (PMID 41440006, 2025). "Schematic illustration of DCBLD1-induced G6PD-mediated reprogramming of PPP metabolism in promoting cervical cancer progression." (PMID 38291438, 2024). "In cervical cancer, the lactylation of DCBLD1 stabilizes its conformation and inhibits the degradation of G6PD, which in turn upregulates the pentose phosphate pathway within tumors and promotes cervical cancer progression." (PMID 39590360, 2024). "DCBLD1, in turn, advances the progression of cervical cancer by increasing the expression and activity of G6PD, impeding its autophagic degradation, and activating the pentose phosphate pathway (PPP)." (PMID 39867891, 2024). "In summary, this study revealed the role of DCBLD1 in promoting the malignant progression of cervical cancer by activating G6PD-mediated PPP in vivo and in vitro." (PMID 38291438, 2024). "Previous literature reported that the elevated expression of G6PD was significantly correlated with the occurrence and deterioration of human cervical cancer, especially with the cervical cancer with HPV16 and HPV18 infection." (PMID 34692493, 2021). "We propose that HPV16 E6 leads to the progression and metastasis of cervical cancer by regulating the expression of host G6PD." (PMID 34692493, 2021). "In this study, we verified that G6PD expression has a strong positive correlation with HPV16 E6 levels in cervical cancer tissues and cells." (PMID 34692493, 2021). "Previous reports have well established the oncogenic effects of E6 oncoprotein or G6PD in cervical cancer." (PMID 34692493, 2021). "The results of this study provide a solid foundation for further exploring the relationship between HPV16 E6 and G6PD in the carcinogenesis of cervical cancer, and supply novel targets for diagnosis and therapy." (PMID 34692493, 2021). "Previous results further proved the positive correlation between the ectopic expression of G6PD and high-risk HPV16- and HPV18-infected cervical cancer." (PMID 34692493, 2021). "The data showed that treatment with either E6 or G6PD contributed to the increase in vitality and mobility and decrease in apoptosis of cervical cancer cells." (PMID 34692493, 2021). "Due to about 85% pentose binding to the DNA derived from the pentose phosphate pathway, G6PD is demonstrated to play important roles in the development and progression of cervical cancer." (PMID 34692493, 2021).
cervical carcinoma (continued). "miR-1-3p has been shown down-regulated in cervical cancer versus normal tissue and its overexpression diminishes proliferation, tumor growth and promotes apoptosis by glucose-6-phosphate dehydrogenase (G6PD) down-regulation functioning as anti-oncomiR." (PMID 28216603, 2017). "In fact, both G6PD and 6PGD have been shown to be increased in cervical carcinoma, as well as in lung tumors." (PMID 28553614, 2017). "miR-1 inhibited proliferation and promoted apoptosis in cervical cancer cells by down-regulating G6PD." (PMID 27861141, 2016). "Here, we explored possible correlations between miRNA and G6PD levels and carcinogenic events in human cervical cancer patients with HR-HPV16/18 infections." (PMID 27861141, 2016). "Our results demonstrate that miR-1 inhibited G6PD expression in human cervical cancer cells and tumors." (PMID 27861141, 2016). "We previously demonstrated that overexpression of G6PD in cervical cancer was positively correlated with cervical cancer development in patients infected with HR-HPV 16/18." (PMID 27861141, 2016). "Furthermore, lactylation has been demonstrated to stabilize DCBLD1, which has been shown to primarily stimulate PPP by upregulating glucose-6-phosphate dehydrogenase (G6PD) expression and enzyme activity, thereby promoting cervical cancer progression." (PMID 40672754, 2025). "Similarly, HPV16 E6 promotes cervical cancer cell proliferation by enhancing G6PD activity to activate PPP." (PMID 41204699, 2025). "In addition, HPV16 E6 can promote G6PD activity by inhibiting its lactylation, which also leads to upregulation of the pentose phosphate pathway and promotes the progression of cervical cancer." (PMID 39590360, 2024). "A study investigated the role of miR-206 and its influence on G6PD in cervical cancer." (PMID 38956668, 2024). "However, the exact mechanisms underlying the abnormal expression of G6PD and the possible effects between HPV E6 and G6PD in the progress and deterioration of high-risk HPV16 infected cervical cancer are still an unsolved mystery." (PMID 34692493, 2021). "On the basis of the HPV E6 overexpression by pcDNA E6 plasmid, the G6PD overexpression and/or G6PD siRNA interference were also introduced in the HeLa cells to determine whether G6PD was regulated by E6 in the progress of cervical cancer." (PMID 34692493, 2021). "It is interesting that HPV16 E6 regulated the G6PD expression in cervical case and HeLa cells, which might be involved in the carcinogenesis of cervical cancer." (PMID 34692493, 2021). "Given those, the results revealed that HPV16 E6 had a function to act as a regulatory factor and alter the viability and mobility of cervical cancer cells by regulating the expression of G6PD, which eventually induced the progression and metastasis of cervical cancer." (PMID 34692493, 2021). "Considering those, there has been an international consensus that G6PD is a novel biomarker of diagnosis and prognosis and may be used as a potential candidate for cervical cancer treatment." (PMID 34692493, 2021). "In addition, regulating the expression of HPV16 E6 significantly affected the proliferation, apoptosis, migration, and invasion in the cervical cancer HeLa cells, as well as the transcript and protein levels of G6PD." (PMID 34692493, 2021). "miR-1 overexpression promoted apoptosis by targeting G6PD in cervical cancer cells." (PMID 29581534, 2018). "In this study, we demonstrate that miR-1 might suppress the development and progression of HR-HPV 16/18-infected cervical cancer by targeting G6PD." (PMID 27861141, 2016). "Down-regulation of miR-1 increased G6PD expression in cervical cancer cells." (PMID 27861141, 2016). "Together, these in vitro and in vivo results indicate that miR-1 might suppress the development and progression of HR-HPV-16/18+ cervical cancer by targeting G6PD." (PMID 27861141, 2016). "In this study, we demonstrated that G6PD is also a direct target of miR-1 in cervical cancer cells." (PMID 27861141, 2016).